POLG (DNA polymerase gamma, catalytic subunit)
Diseases named in the same sentence as POLG in open-access papers (continued):
Sharing a sentence is not in itself a finding about the gene and the disease.
essential tremor (1 paper, 2024). A relatively common disorder characterized by a fairly specific pattern of tremors which are most prominent in the upper extremities and neck, inducing titubations of the head. "One out of the five (1/5) patients carrying a pathogenic variant of POLG presented an essential tremor that could fit with the phenotypic spectrum of POLG." (PMID 39595984, 2024).
female infertility (1 paper, 2018). Diminished or absent ability of a female to achieve conception. "In mitochondrial DNA (mtDNA) mutator mice (PolgD257A/D257A), which harbor a mutation in the proofreading mtDNA polymerase-gamma (POLG), mitochondrial mutations rapidly accumulate, resulting in a premature aging phenotype and female infertility." (PMID 30240410, 2018).
fibromatosis (1 paper, 2024). A poorly circumscribed neoplasm arising from the soft tissues. "Of these, second hits in the tumors were identified in two patients, harboring germline variants in the KCNQ1 and POLG genes and diagnosed with fibromatosis and GIST, respectively." (PMID 39594770, 2024).
folate deficiency (1 paper, 2018). A nutritional condition produced by a deficiency of FOLIC ACID in the diet. "Cerebral folate deficiency is reported in several types of mitochondrial disease, including POLG mutations, ranging from mild deficiency to more severe forms that can mimic primary folate disorders, such as those due FOLR1 mutations." (PMID 30167885, 2018).
gastric tumor (1 paper, 2017). "In conclusion, we suggest a novel mechanism by which curcumin inhibited gastric tumor growth through excessive ROS generation resulting in depletion of POLG and mtDNA, and the subsequent disruption of cellular bioenergetics." (PMID 28359291, 2017). "Together, our data suggest a novel mechanism by which curcumin inhibited gastric tumor growth through excessive ROS generation, resulting in depletion of POLG and mtDNA, and the subsequent disruption of cellular bioenergetics." (PMID 28359291, 2017).
Insulin resistance (1 paper, 2020). Increased resistance towards insulin, that is, diminished effectiveness of insulin in reducing blood glucose levels. "Our findings indicate that increased mtDNA point mutations fail to induce insulin resistance, adiposity, or broad changes in markers of mitochondrial function related to the genome, proteome, and metabolome of postabsorptive 6‐month‐old PolG+/mut mice." (PMID 33049094, 2020). "Based on previous reports, we hypothesized that an increased mtDNA point mutation frequency in PolG+/mut mice would promote mitochondrial dysfunction and accelerate the development of insulin resistance during aging." (PMID 33049094, 2020).
leprosy (1 paper, 2025). Leprosy is a chronic infectious disease affecting primarily the skin and peripheral nervous system. "Mutations in genes like PARK2, which encodes the mitophagy factor Parkin, TFAM, which encodes a histone-like protein of the mitochondrial genome, as well as POLG, have been linked to leprosy susceptibility or severity of disease." (PMID 39969190, 2025).
lung adenocarcinoma (1 paper, 2016). A carcinoma that arises from the lung and is characterized by the presence of malignant glandular epithelial cells. "The interaction between EXOG with APE1, PolG or Lig3, but not between nuclear-specific DNA repair enzymes FEN1 and PolB, was markedly reduced by H2S biosynthesis inhibition in lung adenocarcinoma (but not in normal epithelial cells)." (PMID 27808278, 2016).
metabolic myopathy (1 paper, 2024). A group of rare inherited disorders characterized by a deficiency of enzymes that are involved in metabolic pathways that affect muscles. "One was diagnosed with metabolic myopathy and was homozygous for the POLG variant G268A." (PMID 38055022, 2024).
pancreatic cancer (1 paper, 2025). "Previous studies have indicated that in pancreatic cancer, both the mRNA and protein expression levels of POLG are obviously greater in tumor tissues than in normal tissues and that high POLG expression is positively related to poor patient prognosis." (PMID 41293266, 2025).
Perrault syndrome (1 paper, 2024). Perrault syndrome (PS) is characterized by the association of ovarian dysgenesis in females with sensorineural hearing impairment. "Mitochondrial dysfunction is present in some genetic diseases, such as Perrault syndrome, individuals with POLG mutations, and individuals with CLPP mutations, all exhibiting clinical phenotypes of ovarian dysfunction and infertility." (PMID 38694941, 2024).
Progressive encephalopathy (1 paper, 2020). "Seizure management is extremely challenging in patients who harbor POLG variants, and often futile in those presenting with recurrent SE and progressive encephalopathy." (PMID 33113942, 2020).
progressive myoclonus epilepsy (1 paper, 2026). A rare group of disorders characterized by the development of myoclonic and tonic-clonic epileptic seizures associated with progressive degeneration of the nervous system. "This may contribute to seizure susceptibility, a hallmark clinical feature in many POLG‐related syndromes, including Alpers–Huttenlocher syndrome and progressive myoclonus epilepsy." (PMID 41355579, 2026).
rickets (1 paper, 2024). Bone softening and weakening usually caused by deficiency or impaired metabolism of vitamin D. Deficiency of calcium, magnesium, or phosphorus may also cause rickets. "These molecular defects cause abnormal functions of the cartilage extracellular matrix (COMP), paracrine signalling factors (PHEX, FGFR3-related rickets), transcriptional regulation (LZTR1), histone methylation (KMT2A), posttranslational modification (NAA15), and mtDNA replication and repair (POLG)." (PMID 39415983, 2024).
sarcoma (1 paper, 2024). A usually aggressive malignant neoplasm of the soft tissue or bone. "Both germline and somatic hits were found in the ATM, CDC73, MLH1, MSH6, POLG, and KCNQ1 genes, which have no previously known connection with sarcoma." (PMID 39594770, 2024).
Sepsis (1 paper, 2015). Sepsis is defined as life-threatening organ dysfunction caused by a dysregulated host response to infection. "The Western blot analysis showed that sepsis reduced their contents about 48% in POLG, 26% in AP-endoneclease, 11% in OGG1 and 25% in UNG1." (PMID 26448624, 2015).
soft tissue tumors (1 paper, 2024). "The POLG germline variant identified in our study is reported as pathogenic in mitochondrial disease cohorts by multiple submitters in ClinVar, and somatic variants in POLG are reported in 1% (10/902) of soft tissue tumors in COMIC, of which 30% (3/10) are GISTs." (PMID 39594770, 2024).
spinocerebellar ataxia type 20 (1 paper, 2017). Spinocerebellar ataxia type 20 (SCA20) is a very rare subtype of type I autosomal dominant cerebellar ataxia (ADCA type I). "Three main known etiologies may be considered: Alexander disease, POLG mutation, and spinocerebellar ataxia type 20 (SCA20)." (PMID 28706504, 2017).
testicular seminoma (1 paper, 2012). A malignant germ cell tumor arising from the testis. "Another study suggested that the CAG polymorphism in POLG may be a contributing factor in the pathogenesis of testicular seminoma." (PMID 22276120, 2012).
toxicity (1 paper, 2014). The degree to which an agent can damage an organism. "A profound toxic reaction on administration of VPA has been observed in several patients carrying POLG mutations, and heterozygous genetic variation in POLG has been strongly associated with VPA-induced liver toxicity." (PMID 24725338, 2014).
urea cycle disorder (1 paper, 2023). A genetic inborn error of metabolism characterized by the deficiency of one of the enzymes necessary for the urea cycle. "In the case of valproate, pharmacogenetic testing is helpful for certain genes, i.e., POLG, OTC, and CSP1, when a mitochondrial disorder or a urea cycle disorder is suspected." (PMID 36873203, 2023).
mitochondrial disease (98 papers, 2010 to 2026). "Mutations in the POLG gene are the most common causes of inherited mitochondrial disorders, affecting up to 2% of the population and resulting in a broad spectrum of mitochondrial diseases." (PMID 39958089, 2025). "As her clinical condition deteriorated, she progressed to super-refractory status epilepticus, ultimately leading to the diagnosis of an underlying POLG-related mitochondrial disease." (PMID 39958089, 2025). "Mutations in POLG are the commonest cause of mitochondrial disease and often considered a paradigm for mitochondrial disease in general." (PMID 38904024, 2024). "Mutations in human POLG or POLG2 lead to a group of multi-organ mitochondrial diseases with Mendelian inheritance, collectively named POLG-related disorders, characterized by multiple deletions and/or depletion of mtDNA." (PMID 38643274, 2024). "One of the most common mitochondrial diseases is caused by mutations in the POLG gene encoding the catalytic subunit of the mitochondrial DNA polymerase gamma (Pol γ), which is responsible for replication and repair of mitochondrial DNA (mtDNA)." (PMID 38445970, 2024). "Mutations in the POLG gene, which encodes the catalytic subunit of polymerase γ, are the primary cause of inherited mitochondrial diseases." (PMID 38904024, 2024). "The majority of the core proteins of the mtDNA replication and expression machinery are dedicated mitochondrial proteins, with pathological variants resulting solely in mitochondrial disease phenotypes, including POLG, POLG2, TWINKLE, MGME1 and POLRMT." (PMID 37013609, 2023). "POLG mutations are the most common cause of inherited mitochondrial disease, and the number of individuals harboring a POLG mutation is estimated to be ∼2% of the population." (PMID 35760101, 2022). "The aim of this systematic review is to summarize the efficacy of diet treatment on seizure frequency, clinical symptoms, and potential deleterious effect of liver involvement in patients with mitochondrial diseases caused by pathogenic POLG variants." (PMID 36142570, 2022). "More than 180 POLG variants have been identified, and found to cause a wide range of mitochondrial diseases (MD)." (PMID 36142570, 2022). "In summary, we engineered a cell line model of a heterozygous POLG Y955C mitochondrial disease mutation in the SJCRH30 cell line." (PMID 35760101, 2022). "One of the most common nuclear gene-related mitochondrial disease, dominant variants in the POLG gene, have been linked with primary ovarian insufficiency and primary testicular failure." (PMID 35552684, 2022). "POLG mutations impair the replication of mtDNA and cause a range of mitochondrial diseases many of which affect the brain." (PMID 34631714, 2021). "In humans, mutations in the POLG gene underlie a set of mitochondrial diseases characterized by mitochondrial DNA (mtDNA) depletion or deletion and multiorgan defects, named POLG disorders, for which an effective therapy is still needed." (PMID 33469036, 2021). "Mutations in the human POLG gene cause a series of mitochondrial diseases with Mendelian inheritance, collectively named POLG-related disorders, characterized by mtDNA depletion (MDD) or accumulation of multiple deletions." (PMID 33469036, 2021). "Mutations in POLG are associated with a wide range of mitochondrial diseases that form a continuum from catastrophic early-onset hepato-cerebral degeneration to late-onset progressive external ophthalmoplegia." (PMID 34631714, 2021). "As another nematode model carrying heteroplasmic mtDNA mutations, ‘mutator worms’ carry a POLG mutation [polg-1(srh1)] analogous to that of mutator mice and recapitulate major hallmarks of mitochondrial diseases." (PMID 34114603, 2021). "Pathogenic mutations in POLG are the most common cause of mitochondrial disease linked to improper maintenance of the mitochondrial genome." (PMID 32943091, 2020).
mitochondrial disease (continued). "The role of mitophagy in mitochondrial disease such as those caused by POLG mutation remains, however, unclear." (PMID 32840960, 2020). "Using this design, we evaluated the response to PT1 using cells from patients with SURF1 and POLG-deficiency, two distinct causes of mitochondrial disease." (PMID 33052980, 2020). "Almost 200 POLG mutations have been reported and these are the most common causes of mitochondrial disease." (PMID 32269576, 2020). "At the same time, FTIR spectroscopy differentiated single mtDNA deletion and mutations in POLG, the most common nuclear gene associated with mitochondrial diseases, with high sensitivity and specificity." (PMID 33352713, 2020). "Disorders related to POLG functionality are a major cause of mitochondrial disease delivering varying phenotypes in humans." (PMID 33049094, 2020). "Inherited mitochondrial disorders are most commonly caused by POLG mutations (accounting for 10% of adult mitochondrial disease cases), with as many as 2% of the population carrying these mutations." (PMID 33113942, 2020). "His hearing deficit was probably due to the POLG-associated mitochondrial disease because hearing loss is a characteristic finding in patients with PEO, especially autosomal dominant PEO." (PMID 32042919, 2020). "Since mutations in POLG are one of the most common causes of mitochondrial disease, we wanted to study the impact of gender, puberty, and pregnancy on POLG disease with the aim of providing insights to guide physicians responsible for their management." (PMID 32949115, 2020). "Since mutations in POLG have been well documented in mitochondrial disease, we surveyed reported Clinvar variants within ORF-Z or ORF-Y that are synonymous or in the 5′-UTR with respect to the main ORF." (PMID 32138667, 2020). "The c.1399G>A mutation in exon 7 of POLG produces an alanine to threonine substitution (A467T) at a highly conserved site and is the most frequent pathogenic mutation in POLG-related mitochondrial disease." (PMID 26735972, 2016). "All 5 children with MLD had MRI, which in 1 case (who had POLG mutation) showed symmetrical posterior midbrain changes similar to those reported in mitochondrial disease." (PMID 27482763, 2016). "Mutations in the nuclear gene POLG (encoding the catalytic subunit of DNA polymerase gamma) are an important cause of mitochondrial disease." (PMID 26735972, 2016). "Three patients had a mitochondrial disease linked to a large mtDNA deletion (patient P02) or to mutations in POLG (patient P04) or SUCLG1 (patient P06)." (PMID 26742794, 2016). "In search of new possibly pathogenic variants which can be modelled in S. cerevisiae, POLG sequence analysis was conducted for 60 patients with mitochondrial disease." (PMID 26077851, 2015). "POLG, a nuclear gene, is a major locus for human mitochondrial disease, and the carrier rate for POLG mutations is greater than 2%." (PMID 26519465, 2015). "Recessive mutations in POLG (0.6/100,000) are also emerging as an important cause of mitochondrial disease in the North East of England." (PMID 25652200, 2015). "Among the POLG mutations associated with mitochondrial disease, many have been characterized biochemically and shown to disrupt polymerase activity." (PMID 25340760, 2014). "Mutations in the POLG gene have emerged as one of the most common causes of inherited mitochondrial disease in children and adults." (PMID 21235791, 2011). "POLG mutations impair mitochondrial DNA replication and cause diverse mitochondrial diseases." (PMID 40404629, 2025). "Mutations in POLG, which encodes POLγA, lead to various mitochondrial diseases." (PMID 40404629, 2025). "Mutations in POLG represent the most common cause of inherited mitochondrial disease." (PMID 41226312, 2025). "POLG mutations represent the most prevalent single-gene cause of mitochondrial disease." (PMID 41245005, 2025).
mitochondrial disease (continued). "PEO is a mitochondrial disease caused by either mutations, rearrangements, or deletions in mitochondrial DNA (mtDNA), or mutations in nuclear genes that participate in the maintenance of mtDNA (e.g., POLG, TWNK)." (PMID 41149856, 2025). "POLG pathogenic variants are among the more common causes of inherited mitochondrial diseases." (PMID 39574155, 2024). "Finally, POLG-related disorders encompass various syndromes linked to a mutation in the nuclear POLG gene, representing the most prevalent single-gene cause of mitochondrial disease." (PMID 38689878, 2024). "However, in POLG associated mitochondrial disease, the SLEs start later than other neurological features and motor seizures and status epilepticus are more common." (PMID 39666093, 2024). "In addition, greater than 300 pathogenic mutations localize to the nuclear POLG gene alone and are associated with different types of mitochondrial disease, including mtDNA depletion and deletion disorders." (PMID 35760101, 2022). "POLG mutations may lead to mtDNA point mutations, multiple deletions or quantitative depletion, and are the most common cause of primary mitochondrial diseases." (PMID 36362003, 2022). "A recent review of the literature identified 14 patients with mitochondrial disease and adrenal insufficiency; of these patients, 10 harbored mtDNA deletions, 2 patients harbored recessive POLG variants, 1 harbored recessive GFER variants, and 1 carried the m.8344A > G pathogenic variant." (PMID 35552684, 2022). "Therefore, our goal was to engineer a cell line model harboring the POLG Y955C variant to have an unrestricted number of cells to understand better the cellular and molecular impacts of this mitochondrial disease mutation." (PMID 35760101, 2022). "A cohort of nine PD cases and four mitochondrial disease cases with POLG mutations were included." (PMID 33980828, 2021). "Mutations in the POLG gene cause mitochondrial disease with devastating phenotypes in patients." (PMID 32840960, 2020). "Over three hundred missense mutations in POLG have been reported to cause a wide spectrum of mitochondrial diseases with ages of onset ranging from early (childhood myocerebrohepatopathy or Alpers-Huttenlocher syndrome) to late (ataxia neuropathies or progressive external ophthalmoplegia)." (PMID 32943091, 2020). "Gene variations (like those seen in POLG encoding p140 R964C, R953C, and E1143D/G) may exacerbate mitochondrial disease-like phenotypes in HIV-infected patients treated with NRTIs." (PMID 29214156, 2017). "Thus, the majority of individuals with heterozygous POLG mutations are thought to be asymptomatic for mitochondrial disease." (PMID 26519465, 2015). "Also, mutations in genes encoding the mitochondrial replisome, including DNA polymerase γ (pol γ, encoded by POLG), contribute to mitochondrial diseases characterized by mtDNA depletion, deletions, or point mutations." (PMID 25340760, 2014). "In these patients, brain MRI revealed characteristic features for mitochondrial diseases due to POLG mutations including cortical signal intensities, brain atrophy, basal ganglia changes, but without liver manifestation as has been the case in some Alpers patients." (PMID 23448099, 2013). "POLG mutations are well-known to cause either autosomal dominant (ad) or recessive (ar) mutations associated with a broad phenotypic spectrum and may account for up to 25% of all adult presentations of mitochondrial diseases." (PMID 31991853, 2020). "Little is known about the susceptibility of individuals with POLG mutations to stressors that include environmental contaminants, drug exposures and dietary deficiencies, which could address the variability in mitochondrial disease phenotypes in people with the same POLG mutation." (PMID 26519465, 2015).